NRAS (NRAS proto-oncogene, GTPase)
Diseases named in the same sentence as NRAS in open-access papers (continued):
Sharing a sentence is not in itself a finding about the gene and the disease.
tumor (continued). "All the tumor areas sampled were analyzed for KRAS, BRAF, PIK3CA, and NRAS mutations." (PMID 29774112, 2018). "Moreover, our analysis identifies consistent cross-cancer effects for 4 genes (FGFR1, ERRB2, IDH1, KRAS/NRAS) in 14 tumor types." (PMID 30442178, 2018). "Considering the results that wild-type H and NRAS is required for the mutant KRAS-induced tumor progression, degradation of wild-type H and NRAS together with the mutant KRAS provide a benefit for the application of KYA1797K and derivatives as anti-cancer drug candidates." (PMID 29872723, 2018). "Not only can these clones be statistically explained with allele dropout, but they also do not fit with a model of serial mutation acquisition predicted by the presence of the NRAS, ASXL1, and IDH2 triple-mutant clone comprising 64% of the tumor at this time point." (PMID 30087104, 2018). "Tumor genotyping is become standard practice for CLM and clinicians often have information on the mutational status of oncogenes, including the KRAS, BRAF, PIK3CA, and NRAS oncogenes." (PMID 29774112, 2018). "Activating RAS mutations (11 NRAS and 1 KRAS mutation) were identified in 12/63 (19%) tumours." (PMID 29559732, 2018). "The most frequently mutated genes across all tumor types included KRAS (30 patients), PIK3CA (16 patients), BRAF (6 patients), EGFR (5 patients), NRAS (4 patients) and ERBB2 (3 patients) whereas CCND1, ERBB2, EGFR and MYC were the genes most frequently subjected to copy number gain." (PMID 29854313, 2018). "On contrary, the levels of cfDNA mutations in patients without a prior KRAS/NRAS/BRAF/PIK3CA tumor mutation were 10-fold lower than the mutation cutoff (p = 0.002)." (PMID 27852040, 2017). "Mouse models of spontaneous lung metastasis revealed that mutant or overexpressed NRAS promotes lung colonization by regulating interleukin‐8‐related chemokine expression, thereby initiating interactions between tumor cells, the pulmonary vasculature, and myeloid cells." (PMID 28341702, 2017). "In a direct comparison of the single-cell data and an immunofluorescence analysis of the original tumor of the BRAF/NRAS wild type tumor sample, we provided strong evidence that the cell composition revealed by single-cell RNA-seq reflects the actual situation in the original primary tissue." (PMID 27903987, 2017). "There were three pairs of genes that were mutated in a mutually exclusive pattern in tumor samples (n = 412): BRAF and NRAS mutations (Bonferroni adjusted p-value < 0.05), BRAF and NF1 mutations (Bonferroni adjusted p-value < 0.05), and NRAS and PTEN mutations (Bonferroni adjusted p-value < 0.05)." (PMID 29383127, 2017). "We show that these cells infiltrate and possibly predispose the local microenvironment for the successful settling of disseminated NRAS‐mutant tumor cells, and include CD45+CD11b+Ly6c+ and CD45+CD11b+Ly6g+ hematopoietic as well as CXCR2+CD34+ endothelial progenitors." (PMID 28341702, 2017). "We document that mutant or overexpressed NRAS is required for this capability of tumor cells and that it suffices to transmit it to cancer cells without NRAS mutations or even to benign cells." (PMID 28341702, 2017).
tumor (continued). "We observed a perfect match (100% specificity and sensitivity of the BEAMing technique compared to Ion Torrent and Cobas FDA-approved tumor mutation assessment kits) in the results of our analysis of KRAS, NRAS, PIK3CA and BRAF mutations in tumor and prior treatment plasma samples." (PMID 27852040, 2017). "Altogether, above results suggest that loss of epidermal Rxrα when combined with oncogenic NRAS and activated CDK4 results in melanomagenesis, which is further accelerated by a single neonatal UVB exposure reducing the tumor latency as shown in the Kaplan Meier curve." (PMID 29121869, 2017). "The NCCN guidelines state that all patients with metastatic CRC should have tumor tissue genotyped for KRAS, NRAS, and BRAF mutations, and patients with any known KRAS or NRAS mutation should not be treated with anti-EGFR therapy such as cetuximab and panitumumab." (PMID 29212173, 2017). "In conclusion, NRAS promotes the colonization of the lungs by various tumor types in mouse models." (PMID 28341702, 2017). "The tumor was also tested for mutations in exons 2, 3, and 4 of the KRAS and NRAS genes, codon 600 of the BRAF gene, and exons 10 and 21 of the PIK3CA gene, and showed a mutation in PIK3CA exon 10, namely the c.1624G>A, p.Glu542Lys (previously reported by our group 15)." (PMID 29072370, 2017). "The mutational status of BRAF and NRAS in the four PTC variants (cPTC, PTMC, PTMC-FV and PTC/FV) was compared to the clinicopathological parameters, including age, gender, tumor size, extracapsular extension, lymphovascular involvement, lymph node metastasis, and multifocality." (PMID 28680105, 2017). "NRAS‐mutation(+) CRC significantly correlated with older age, distal colon, more mucinous component of the tumor, earlier AJCC stage, less lymph node metastasis, and less lymph vessel invasion (P = 0.01, 0.002, 0.02, 0.001, 0.003, and 8 × 10−6, respectively), compared with KRAS‐mutation(+) CRC." (PMID 28378457, 2017). "Equally attractive, Usp9x inhibition may be an effective means of targeting NRAS-mutant and -dependent tumours, a goal that has been particularly elusive with other approaches." (PMID 28198367, 2017). "One reason for this large increase in the number incorrect NRAS genotyping errors was the use by several laboratories of a commercial kit, not designed to identify the particular NRAS mutation, carried by one of the tumours; c.181C > A p.(Gln61Lys)." (PMID 28653203, 2017). "The nodular subtype was more common in BRAF- and NRAS-mutant groups, while there were no major differences regarding other histologic risk factors such as tumor depth or presence of ulceration." (PMID 28797232, 2017). "We cross‐examined the genotype of various tumor cells with their ability for automatic pulmonary dissemination, modulated NRAS expression using RNA interference and NRAS overexpression, identified NRAS signaling partners by microarray, and validated them using Cxcr1‐ and Cxcr2‐deficient mice." (PMID 28341702, 2017). "Of the three patients who had objective responses, one tumour sample showed an NRAS mutation (PR patient), whereas no mutations were detected for the other two patients." (PMID 28152546, 2017). "All of these genes have been associated with tumor growth and progression, and recent studies suggest that additional mutations in KRAS and NRAS, as well as downstream mutations in BRAF or PIK3CA, may cause resistance to anti-EGFR treatment." (PMID 26989027, 2016). "Overall, 38% of patients had KRAS exon 2 mutations, and 10% had RAS mutations beyond KRAS exon 2 (KRAS exon 3 and 4 mutations each in 3% of tumours; NRAS exon 2 and 3 mutations each in 2% of tumours; no tumour was found to carry an NRAS exon 4 mutation)." (PMID 27764839, 2016). "None of the tumor tissue samples of all 46 patients showed evidence of mutations in the cetuximab-interacting EGFR ectodomain or KRAS/NRAS." (PMID 27119512, 2016).
tumor (continued). "Recently, several miRNAs–such as miR-181d, let-7 and miR-143–have been reported to suppress RAS expression, and thus act as tumor suppressors; this suggests that the dysregulation of miRNAs targeting NRAS may have an important role in carcinogenesis." (PMID 26799668, 2016). "Further, NRAS protein levels are dysregulated in several tumor cells." (PMID 27556696, 2016). "Comparing tumor subgroups of NRAS mutated with NRAS wildtype, no significant expression differences were found except for SOX5 which was significantly overexpressed in NRAS mutated samples (p = 0.05)." (PMID 26927636, 2016). "By isolating and sequencing colonies derived from 23 single-cell clones of the resistant late metastasis 6 from patient 1, we could show for the first time that both activating MAPK mutations (NRAS and BRAF) were present in a single tumor cell." (PMID 27791198, 2016). "NRAS has been reported to act as an oncogene in various tumor cells." (PMID 27556696, 2016). "Mutations in KRAS, NRAS, BRAF, and PIK3CA genes were evaluated for association with several pathological parameters: sex, age at diagnosis, anatomical location of primary CRC, tumour grading, AJCC stage of the disease." (PMID 27737711, 2016). "In order to investigate the evolution of the NRAS/BRAF double mutated cancer cells within a patient, we analyzed tumor DNA for the presence of double mutations in all available histological and frozen material from patients 4, 5, 6, 7 and 8 before and after BRAF inhibitor treatment." (PMID 27791198, 2016). "In patients whose tumours harbour NRAS mutations, there appear to be no other obvious driver mutations." (PMID 26410619, 2015). "These events may include mutations in key genes that when estimated as % of the tumor population emerge as subclonal events in different MM patients: KRAS (20–72%), NRAS (32–96%), BRAF (36–92%) or DIS3 genes (29–81%)." (PMID 25929340, 2015). "Previous work showed that YAP inhibition in RD (NRAS-mutant) xenografts decreased tumor burden." (PMID 26496700, 2015). "The patient’s brain metastasis was a BRAF V600E mutated, NRAS WT, TERT C250T mutated tumor with evidence of germline SNPs that may be associated with improved OS." (PMID 26597176, 2015). "For instance, while fractional abundance of ATM, NRAS and IGF1R mutations in the primary tumour was 35%, 20% and 2%, respectively, the prevalence of these mutations in the corresponding plasma samples was 0.05, 0.07 and 0.07%, whereas in the sputum, mutations fractions were 0.04, 0.03 and 0.03%." (PMID 26374070, 2015). "Similarly, mRNA and protein levels of CAV1 and β-catenin (total and pSer675 protein) were also increased in NRAS-ΔPTEN tumours compared with NRAS." (PMID 26307673, 2015). "Inclusion of other risk factors in the model (age, sex, the degree of tumor infiltrating lymphocytes, BRAF/NRAS mutation status and tumor regression) did not result in an increase of the AUC." (PMID 25871393, 2015). "No mutation was identified either in BRAF (codon 600) or NRAS genes (codons 12, 13, 61 and 146) in this tumor set." (PMID 26437257, 2015). "As we had paired tumor samples for 30 patients, we were able to examine intrapatient heterogeneity of mutant BRAF as determined with both pyrosequencing and IHC, and in some cases NRAS mutation as determined with pyrosequencing." (PMID 25526463, 2014). "In tumours that had no BRAF or NRAS mutation, low PTEN was significantly associated with poor overall survival [HR 95%CI)=0.27 (0.12, 0.64), P=0.003]." (PMID 24830350, 2014). "The presence of NRAS mutations was inversely correlated with tumor size, regardless of the presence of malignancy." (PMID 25254041, 2014). "Furthermore, transition/transversion analysis led to a novel finding that tandem CC>TT/GG>AA mutations (UV damage signature) were more common in tumours arising in severely sun damaged skin and in BRAF/NRAS wild-type tumours." (PMID 24752294, 2014).
tumor (continued). "Tumor size was significantly larger in cancers without NRAS mutations than in those with mutations (P = 0.012)." (PMID 25254041, 2014). "Low PTEN was associated with poor survival overall but the effect was absent in BRAF and NRAS-mutated tumours, and only statistically significant in tumours without BRAF or NRAS mutations." (PMID 24830350, 2014). "Thus, for tumors harboring NRAS or BRAF mutations, activation of this pathway is thought to play a key role in driving tumor growth." (PMID 23673558, 2013). "Moreover, there was a strong correlation between tumor NRAS and BRAF mRNA expression levels (rs = 0.627; p < 0.001)." (PMID 23673558, 2013). "This suggests that a large proportion of BRAF mutant cells in the resistant tumor did not harbor the NRAS mutation." (PMID 22235286, 2012). "We report here the development, validation, and clinical implementation of a multiplexed assay designed to simultaneously detect 43 recurrent mutations in BRAF, KIT, NRAS, GNA11, GNAQ, and CTNNB1 using tumor-derived DNA from formalin-fixed paraffin-embedded (FFPE) tissues." (PMID 22536370, 2012). "This possibility is further supported by recent data from a large retrospective study of BRAF and NRAS genotyping results demonstrating a small fraction of patients in which both BRAF and NRAS mutations were detected in their tumor specimen, possibly due to intratumor heterogeneity." (PMID 22235286, 2012). "Across tumor types, we demonstrated a higher prevalence of RAS (KRAS, NRAS) or BRAF mutations (47%) and KRAS mutations (38%) in patients with mutant PIK3CA compared to those with wtPIK3CA (mutant RAS or BRAF present in 24%, p = 0.001; mutant KRAS present in 16%, p = 0.001)." (PMID 21829508, 2011). "However, knocking down KRAS in HCT116 and NRAS in IPC298 led to a significant delay in tumor growth, indicating the requirement of KRAS in HCT116 and NRAS in IPC298 for tumor growth in vivo." (PMID 19492075, 2009). "Therefore, we hypothesised that the tumour acquired additional aberrations which, together with the NRAS Q61H, would contribute to the aggressive disease progression." (PMID 41168392, 2025). "The tumor lineage and aggressive potential was confirmed by extensive genetic testing revealing a high tumor mutational burden and pathogenic mutations in TERT, NRAS, and NF1, alongside alterations in PBRM1 and FAT1, which may contribute to the tumor's unique morphology." (PMID 40125165, 2025). "Moreover, although we report the coexistence of BRAF and NRAS mutations within the same tumor, this does not necessarily imply these mutations can co-occur within single cells, as each tumor cell has its transcriptional repertoire that dictates its fate." (PMID 38396984, 2024). "In addition, an NRAS Q61R mutation not present in the tumor tissue was found in both ctDNA and CTCs." (PMID 38898234, 2024). "While the enrollment criteria required patients to have RAS WT tumor tissue based on local assessment using a validated test, a small proportion of patients was found to have RAS mutations (6.0% with KRAS and 1.4% with NRAS mutations) according to the ctDNA test." (PMID 38347302, 2024). "However, HER2 testing is not indicated if the tumor is already known to have a KRAS/NRAS or BRAF mutation." (PMID 39519088, 2024). "In this manuscript, we performed a relatively large-scale study to determine the correlation between the percentage of tumor cellularity estimated by certified anatomic pathologists and VAFs of well-studied driver mutations detected in key oncogenes (i.e., BRAF, EGFR, KRAS, and NRAS)." (PMID 38397405, 2024). "Finally, tumor SP‐06 presented genetic alterations in genes NF2, SMARCA4, and NRAS, which may point to other tumor entities." (PMID 37798904, 2024). "However, overexpression of FASN, either alone or in association with other oncogenes such as c-Met and mutant NRas, did not drive liver carcinogenesis in the mouse, assigning a tumor-supporter role rather than a bona fide oncogenic function to FASN." (PMID 39064589, 2024).
tumor (continued). "The recurrent tumor was not genotyped and the malignant cells carrying the NRAS p.G12D mutation could then be cleared during surgery or adjuvant chemotherapy." (PMID 38339300, 2024). "Importantly, of the tumor collected at progression in cohort 1, we found 2 patients to have new tumor mutations that were not present at baseline: NRAS and TERT promoter." (PMID 39446377, 2024). "Indeed, by immunohistochemistry, we could confirm an enhanced cytoplasmic positivity for DUSP6 in NRAS-induced tumours." (PMID 37946160, 2023). "The combination of crizotinib with the ERBBi afatinib demonstrated synergistic cytotoxic effects, significantly reducing 2D and 3D invasion, migration and colony formation independent of BRAF/NRAS mutation status, and resulting in decreased tumour volume in vivo." (PMID 37181747, 2023). "This included collating studies of Sanger sequencing hot spot regions in BRAF, NRAS, and KIT, identifying rare but recurrent functionally relevant non‐hot spot variants, which otherwise would not have been uncovered, highlighting the importance of analyzing larger tumor collections." (PMID 35229492, 2022). "Therefore, we hypothesized that circRANGAP1 accelerated the HCC progression by regulating miR-27b-3p/NRAS axis, activating the downstream MAPK signaling pathway, and affecting the infiltration levels of tumor-associated macrophages." (PMID 36348379, 2022). "Since mutations in BRAF and NRAS comprehensively account for about 70% of melanoma cases, it is tempting to suggest that activation of RAS/RAF/MAPK pathway may as well influence the susceptibility of this tumor type to ferroptosis." (PMID 35912247, 2022). "In addition to a panel of gene analysis of the tumour, mutation analysis of the BRAF, KRAS and NRAS genes and Mismatch Repair (MMR) status (Microsatellite instability, MSI, Immunohistochemistry, IHC, for MMR genes) will be performed on the selected tumour sections." (PMID 34544470, 2021). "Our finding suggests that NRAS mutation might play a negative role in ethnic groups with deeper skin colors and a low tumor mutation burden." (PMID 34290710, 2021). "The tumor of patient 3 showed no mutation in NRAS (tumor cell content of the whole section: 30%)." (PMID 34072863, 2021). "In addition to KRAS, both HRAS and NRAS have all been reported to dimerize, but the biologic effects of RAS dimerization and whether a similar mechanism underlies the tumor suppressive functions of WT HRAS and NRAS are untested." (PMID 33924994, 2021). "In tumors with mutations of KRAS, NRAS, PIK3CA, or BRAF, the proportion of VAF with different mutations in tumor cell samples of the same patient varies significantly, which may also reflect the ITH of tumor cells." (PMID 32853464, 2020). "Only a single plasma sample had a KRAS Mx mutation which was also seen in the tumor; the NRAS Q61 mutation was seen in 3 cases, both in cfDNA and tumor DNA; and no mutations in NRAS G12/G13 were detected in any of these 17 cfDNA samples or their matched tumors." (PMID 32284750, 2020). "It is important to know tumor genetic profile as genetic mutations have a fundamental impact on the selection of targeted therapy such as BRAF/MEK inhibitors in BRAF-mutated tumors, tyrosine kinase inhibitors in KIT-mutated tumors and MEK inhibitors in NRAS-mutated tumors." (PMID 32637031, 2020). "However, the small size of our study group and lack of statistically significant associations between NRAS mutation status and histological type of the tumor put the importance of this finding into question." (PMID 29682098, 2018). "Therefore, patients with a negative SLNB who harboured a BRAF/NRAS mutation experienced a hazard of disease relapse almost twice that of patients with BRAF/NRAS wild-type tumours." (PMID 29755118, 2018).